ARF6 (ARF GTPase 6)
Diseases named in the same sentence as ARF6 in open-access papers (continued):
Sharing a sentence is not in itself a finding about the gene and the disease.
infection (continued). "As Arf6 is required for anchoring EspG to lipid bilayers in our in vitro reconstitution system, we returned to cell infection to further test the role of EspG." (PMID 33144373, 2020). "To more efficiently assess the role of Arf6, here, we used WT, ΔArf6, and ΔNap1 Hap1 cells, and performed a gentamycin protection assay measuring invasion at different times post infection." (PMID 32252226, 2020). "Arf6 is the predominant Arf found at the plasma membrane and is the major family member bound by EspG during infection." (PMID 31431554, 2019). "During infection, Arf6 was shown to be present on the Salmonella-induced host cell membrane ruffles and co-localized with the SCV 10 minutes postinfection." (PMID 31060328, 2019). "Combined with the observation of accumulated CIE cargo at the SE, these results suggest that infection diminishes the egress of ARF6 and its cargo from the SE." (PMID 30042195, 2018). "Further, and in support of our model, overexpression of TRE17 in infection also decreased the ARF6-EEA1 association to the levels seen in uninfected cells and increased ARF6 concentration at the PM." (PMID 30042195, 2018). "Of note, RAC1 activation is regulated by ARF6 activation, a process we demonstrate to be dysregulated by infection." (PMID 30042195, 2018). "Regardless, the effect of TRE17 on ARF6 trafficking in infection reveals a novel point of control in infection—the sorting of cargo between EEA1 and ARF6 domains." (PMID 30042195, 2018). "Our data suggests that during infection EspG is recruited to ARF6/Rab35 positive endosomal structures through scaffolding with GTP-bound ARF6." (PMID 27261256, 2016). "Our investigation of the small GTPase interacting partners of EspG during infection reveals that EspG modulates an ARF6:Rab35 signaling axis to disrupt recycling endosome function, resulting in the accumulation of recycling cargo within the host cytosol." (PMID 27261256, 2016). "Here we report that EspG interacts specifically with the small GTPases ARF6 and Rab35 during infection." (PMID 27261256, 2016). "As such, it is the interactions with ARF6 and Rab35 that are relevant for EspG's function during infection." (PMID 27261256, 2016). "As early as 10 min post infection, Arf6 was recruited to the plasma membrane at R. typhi entry foci, while Arf5 remained cytoplasmic." (PMID 26291822, 2015). "The effect of Arf6/Q67L on viral protein production and infectious virus titres in HeLa and BSR cells were examined by transfecting with Arf6/Q67L expression plasmid followed by infection with BTV-1." (PMID 23497128, 2013). "Infection of ARF6-KO with both strains showed a significant reduction compared to NTg cells, suggesting that ARF6 might play a role in post-entry steps in Calu-3 cells." (PMID 37342971, 2023). "This host factor is also important for infection in the more physiologically relevant models of human lung Calu3 cells and kidney organoids, suggesting that ARF6 might be an effective therapeutic target." (PMID 37342971, 2023). "However, the suppression of Arf1 and Arf6 also inhibited the establishment of infection, suggesting that these GTPases are also involved in the earliest stages of infection." (PMID 36077391, 2022). "However, knockdown of Arf1 and Arf6 affected the earlier stages of infection, prior expression of MCMV immediate early genes, indicating that they are essential for virus entry or transport to the cell nucleus." (PMID 34440611, 2021). "Arf6 seems to play distinct roles during the infection of different Coxsackieviruses." (PMID 31060328, 2019). "If cargo such as MHC-I or CD98 was directed by infection into EEA1 membranes of a heterotypic SE, then it might be shielded or out of the reach of TRE17, which specifically associates with ARF6-GDP." (PMID 30042195, 2018). "Furthermore, Arf6 is activated early during infection, with GTP-bound Arf6 localized to the R. typhi entry foci." (PMID 27698019, 2016).
infection (continued). "In addition, we identified TFs that were Differentially expressed at 6 h of infection in the R and S cultivars; for example, Nitab4.5_0000315g0090 (ARF6) was up-regulated at 6 h in both cultivars, while Nitab4.5_0002071g0010 (ARF6) was only up-regulated at 6 h in S cultivar." (PMID 38057713, 2023). "However, the knockdown of Arf1 and Arf6 also abolished the establishment of infection." (PMID 34440611, 2021). "Since ARNO has been shown to activate Arf3 and Arf6 in vitro, we examined whether any additional Arf GTPases promote invasion by depleting Arf3, Arf4, Arf5, and Arf6 individually by siRNA transfection of HeLa cells 72 hr before infection with WT Salmonella." (PMID 22341462, 2012). "We therefore sought to determine the role of ARF6 in SARS-CoV-2 endocytosis and, more broadly, infection." (PMID 37342971, 2023). "In conclusion, our study demonstrates a significant role of Arf1, Arf3, Arf4, and Arf6 in the pathogenesis of CMV infection and host cell reorganization during the early phase of infection." (PMID 34440611, 2021). "Nuclear accumulation of ARF6 and its GEF BRAG2 observed at 48 hpi was rarely observed at earlier stages of infection." (PMID 33042998, 2020). "The silencing of Arf6 or the overexpression of Arf6-Q67L or T44N mutants inhibited the HIV-1 envelope induced-membrane fusion, entry, and infection of T lymphocytes." (PMID 31060328, 2019). "The ADAP2 expression is upregulated by type I interferons, and an ADAP2 overexpression restricts infection by dengue virus (DENV) and vesicular stomatitis virus (VSV) via a mechanism that requires intact Arf6 GAP activity." (PMID 31060328, 2019). "Arf6 and ARNO both accumulate at sites of Shigella flexneri entry, and Arf6 is activated in an early stage of infection by these virulent pathogens." (PMID 31060328, 2019). "Opposed to miRNAs induced by V592-infection, the expression of ARF10, NAC1, ARF6 and PHV was significantly reduced (P-value < 0.05, t-test)." (PMID 30181922, 2018). "We found that infection with HCMV results in the aberrant accumulation and retention of both the CIE regulator ARF6 and CIE cargos in enlarged SEs, representing a fate that is shared with clathrin-dependent endocytic (CDE) cargo." (PMID 30042195, 2018). "Heterotypic ARF6/EEA1 vesicles were also enlarged in HCMV-infected cells compared to uninfected cells, suggesting that infection exaggerates this structure." (PMID 30042195, 2018). "To determine if EspG interacts preferentially with GTP-bound ARF6 during infection we assessed the co-immunoprecipitation of EspG by constitutively inactive, GDP-bound (T44N) or constitutively active, GTP-bound (Q67L) ARF6 mutants." (PMID 27261256, 2016). "Treatment of ARF6-KO cells with 10 μM dynasore did not result in changes to infection, further corroborating that dynamin is not involved in SARS-CoV-2 endocytosis in Huh-7 cells." (PMID 37342971, 2023). "Nevertheless, during infection with WT EPEC, EspG localizes to bacterial attachment sites by binding Arf6, and thus both potential Frabin interactors are present together and may well cooperate." (PMID 33144373, 2020). "ARF6 was also found to be the primary interacting partner over an infection time-course from 2.5 to 7.5 h of infection (data not shown), suggesting the ARF6 interaction occurs early during infection and is maintained as infection progresses." (PMID 27261256, 2016). "Control infected cells that were not expressing Arf6/Q67L also showed expression of the viral proteins at the same time of post-infection (lane 2)." (PMID 23497128, 2013). "Rickettsial manipulation of host signaling is currently exemplified at a molecular level by modulation of PI3K and Arf6 activity but is also apparent by noninflammatory changes to transcriptional and proteomic profiles induced by infection (15, 60, 108, –, 110)." (PMID 37855623, 2023).
infection (continued). "Interestingly, knocking down CDC42 or ARF6 suppressed luciferase expression after infection with ANDV pseudovirions, though not with wild-type ANDV virus." (PMID 27780263, 2016). "This does not preclude the stabilization of active ARF6 by EspG from playing another, currently unknown, role during infection." (PMID 27261256, 2016). "IpgD and PI3K activity but, apparently, not Arf6 are required for ARNO recruitment while Arf6 recruitment and infection are inhibited by SecinH3, which blocks ARNO (and other related cytohesins)." (PMID 31060328, 2019). "Overexpression of host ubiquitin-specific protease 6 (USP6), referred to here as TRE17, is sufficient to reverse the retention of ARF6 and of some, but not all, CIE cargos in the context of infection." (PMID 30042195, 2018). "It is also possible that ARF6 and EEA1, while proximal in infection, do not share a contiguous lumen (coupled); if such an event were the case, however, it would be difficult to imagine how a CIE cargo such as MHC-I ultimately partitions with EEA1." (PMID 30042195, 2018). "The role of Arf6 in viral entry was reported for HIV-1, Coxsackievirus A9, Vaccinia viruses, and Epstein–Barr virus infection, although reported mechanisms might not apply to every infected cell." (PMID 34440611, 2021). "Interestingly, knocking down macropinocytosis markers PAK-1, CDC42, and ARF6 did not significantly reduce ANDV infection." (PMID 27780263, 2016).
cardiovascular disease (2 papers, 2016 to 2023). "Studies are also warranted to examine the effects of Arf6 inhibition in other cardiovascular disease-related comorbidities such as metabolic dysfunction." (PMID 37163513, 2023). "Because of the increasing interest in understanding the role of ROS in cardiovascular diseases, we aimed here at examining whether ARF6 could regulate ROS production and ultimately proliferation of VSMC." (PMID 26824355, 2016).
neurodegenerative disease (2 papers, 2016 to 2022). A disorder of the central nervous system characterized by gradual and progressive loss of neural tissue and neurologic function. "Abnormal mGluR induces cell death through glutamate toxicity and is involved in various neurodegenerative diseases, including MS, thus necessitating further studies on the role of tamalin and Arf6 in neurodegenerative diseases." (PMID 36362204, 2022). "Further studies should give us insights into the role of the novel Arf6/retromer/cholesterol connection in the aetiology of neurodegenerative diseases." (PMID 27336679, 2016).
hematological malignancies (1 paper, 2025). "Third, the role of ARF6 in other hematological malignancies merits investigation, given its involvement in multiple solid tumors." (PMID 40275490, 2025).
kidney diseases (1 paper, 2017). "We examined the function of ARF6 in the kidney podocyte because Rac1 was implicated in kidney diseases involving this cell." (PMID 28880939, 2017).
neurological diseases (1 paper, 2016). "The use of pharmacological tools to mimic or revert Arf6 function at synapse opens new therapeutic approaches to correct dysregulations of the Arf6 pathway occurring in human neurological diseases associated with mutations in the Arf6 regulatory genes." (PMID 26731518, 2016).
ARF6 also shares sentences with these, for which no sentence is quoted: renal cell carcinoma (2 papers); acute myeloid leukemia (1); amyotrophic lateral sclerosis (1); aplastic anemia (1); Arterial thrombosis (1); Autoimmunity (1); autosomal recessive periventricular heterotopia (1); bacterial infection (1); cervical cancer (1); Cirrhosis (1); E. coli infection (1); endothelial dysfunction (1); glomerulosclerosis (1); heart development disorder (1); Hodgkins lymphoma (1); Insulin resistance (1); Intellectual disability (1); lymphedema (1); mesenchymal tumors (1); metastatic prostate carcinoma (1); Niemann-Pick Type C Disease (1); Obesity (1); pancreatic ductal adenocarcinoma (1); parasite (1); prostate adenocarcinoma (1); psychiatric diseases (1); retinitis pigmentosa (1); Salmonella Infections (1); synovitis (1); synucleinopathies (1).
A further 6 diseases each share a sentence with ARF6 in 1 paper.